TMDD1 (transmembrane and death domain 1)
Synonyms: C12orf81; hCG1648055
Tractability: Antibody: UniProt predicts a signal peptide or a membrane-spanning region.
Gene: Protein-coding gene on chromosome 12 (51,813,921 to 51,814,925, reverse strand). Ensembl gene ENSG00000284730.
Subcellular location: Membrane
Gene Ontology:
Biological process: signal transduction
Cellular component: membrane
Homologues: Orthologues: chimpanzee TMDD1 (98% identical), macaque TMDD1 (89% identical), zebrafish si:ch211-226m16.3 (23% identical).